TUBB3 (tubulin beta 3 class III)
Diseases named in the same sentence as TUBB3 in open-access papers (continued):
Sharing a sentence is not in itself a finding about the gene and the disease.
cancer (continued). "Our work also provides a rationale for manipulating TUBB3/βIII-tubulin as a biomarker not just for PTX-resistant cancers but also for cross-resistance to a broad class of drugs." (PMID 27284014, 2016). "Taken together, these data indicate that secretome factors from PTX-resistant cancer cells with acquired cross-resistance can sufficiently influence MDR in first-line PTX-resistant cancers cells with impaired FOXO3a-regulated ABCB1 activity and can be predicted by TUBB3 feedback." (PMID 27284014, 2016). "Our findings do not disprove TUBB3 as a predictive biomarker in other cancers, but its role as a biomarker in SCLC may be questionable, as it has such uniformly high expression." (PMID 24396456, 2014). "It is therefore the downregulation of TUBB3, not an increase in proliferation that is responsible for the enhanced chemosensitivity to taxanes observed with restoration of miR-200c to resistant cancer cells." (PMID 20049172, 2010). "Thus, although some cell lines exhibit elevated levels of TUBB3 upon selection with taxol, as was observed with the RPE-20 cell line in this study and a number of other cancer cell lines in other studies, this is by no means a phenomenon that occurs ubiquitously." (PMID 29069726, 2017).
neurological disorders (10 papers, 2012 to 2025). "Understanding its precise role in regulating TUBB3 and other genes implicated in neurological disorders holds the potential to ensure valuable insights pertinent to the formulation of innovative therapeutic approaches in the future." (PMID 39129166, 2025). "Research suggests that miR-200c exerts a negative regulatory effect on TUBB3 expression, with dysregulation of the miR-200c-TUBB3 axis being implicated in the progression of various neurological disorders." (PMID 39129166, 2025). "Dominant mutations in TUBB3 alter microtubule function and behavior, causing a class of neurological diseases called “the TUBB3 syndromes”." (PMID 36557668, 2022). "Missense mutations in the human TUBB3 gene cause a variety of neurological disorders associated with defects in axon guidance and neuronal migration, but the underlying molecular mechanisms are not well understood." (PMID 31226147, 2019). "TUBB3 is a beta-tubulin mainly expressed in nerve cells, and its dysfunction could lead to neurological disorders." (PMID 33917306, 2021). "Recently, mutations in neuronal tubulin genes (e.g. TUBA1A, TUBB2B, TUBB3 and TUBA8) have been identified in patients suffering from nervous system disorders, underlining the importance of tubulin isotypes in MT dynamics during brain development and axon guidance." (PMID 26331477, 2015).
adenocarcinoma (7 papers, 2014 to 2024). A common cancer characterized by the presence of malignant glandular cells. "A total of 280 adenocarcinomas were available for measuring the TUBB3 mRNA in the same TMA format using RNA-Scope technology." (PMID 29383151, 2017). "The results of our study demonstrate that the mRNA- and corresponding immunohistochemical TUBB3 protein expression in adenocarcinomas of the esophagus serve as a prognostic marker." (PMID 29383151, 2017). "Univariate analysis identified disease stage and STMN1 and TS levels as significant prognostic markers for OS in patients with an adenocarcinoma component, and disease stage and VEGFR2 and TUBB3 levels as significant prognostic markers for OS in patients with a non-adenocarcinoma component." (PMID 31653009, 2019). "Additionally, adenocarcinoma patients with negative TUBB3 expression tend to have longer survival times compared to those with positive expression." (PMID 38562930, 2024).
infection (5 papers, 2019 to 2024). The state of being infected such as from the introduction of a foreign agent such as serum, vaccine, antigenic substance or organism. "The analysis also identified four tubulin genes (Tubb2A, Tubb2b, Tubb3 and Tubb4B) which have previously been associated with E. coli pathogenesis, to be up-regulated in the asymptomatic (resilient to infection) dataset." (PMID 30709726, 2019). "By immunostaining with SARS-CoV-2 NP, we observed viral antigen in the TUBB3+ olfactory region 9 hours after infection, but very little NP in the adjacent TUBB3– respiratory epithelium." (PMID 38483537, 2024). "Cells of glial origin, SVGp12, HMC3, or SVGp12 and HMC3 together, significantly reduced the percentage of eGFP+ TUBB3+ SK-N-SH during both Tha-eGFP (adjusted p-value < 0.000016) and Th2P-4M-eGFP infection (adjusted p-value < 0.000016)." (PMID 36680128, 2022). "Upon infection, Tha-eGFP and Th2P-4M-eGFP successfully replicated in Class III Beta-Tubulin-positive (TUBB3+) hiNeurons and Glutamate Aspartate Transporter 1-positive (GLAST-1+) hiAstrocytes." (PMID 36680128, 2022). "We next investigated the kinetics of RNA levels of selected markers for neural progenitors (NES for nestin) and for markers of mature neurons (TUBB3 and RBFOX3 for β3-tubulin and NeuN, respectively) at 24 h, day 3 and 5 after infection, detected by quantitative RT-PCR." (PMID 33490061, 2020).
neurodevelopmental disorder (4 papers, 2019 to 2025). A behavioral and cognitive disorder with onset during the developmental period that involves impaired or aberrant development of intellectual, motor, or social functions. "While we detail here the genetic and epigenetic mechanisms of Pvt1 ME and its functional consequence, there are several aME genes from our list that are associated with neurodevelopmental disorders, such as Grik3, Mettl5, Gap43, and Tubb3." (PMID 41223055, 2025). "TUBB3 is associated with a dominant neurodevelopmental disorder with disrupted neuronal migration and disturbed axonal guidance resulting in malformations of cortical development." (PMID 37234784, 2023). "TUBB3 mutations are associated with a wide range of neurodevelopmental disorders, mainly reflecting defects in axon projection and neuronal migration." (PMID 31226147, 2019).
peripheral neuropathy (3 papers, 2021 to 2025). A disorder affecting the peripheral nervous system. "Needle electromyography was neurogenic when abnormal, and a previously reported sural nerve biopsy from an individual with a peripheral neuropathy secondary to the TUBB3 D417N syndrome was neurogenic." (PMID 34652576, 2021). "While similar, individuals with the TUBB3 R262H syndrome can be distinguished from individuals with the TUBB3 E410K syndrome by the presence of congenital and acquired joint contractures, an earlier onset peripheral neuropathy, impaired gait, and basal ganglia malformations." (PMID 34652576, 2021).
lung (2 papers, 2014 to 2021). "In the same study, the TUBB3 mRNA jumped to nearly 16% of tubulin isoform mRNA expressed in lung malignancies." (PMID 24396456, 2014).
renal disease (2 papers, 2019 to 2021). "While it remains unknown whether this was related to TUBB3 Arg262His, no other subjects have a history of renal disease, and at least three (XI, XII, XIII) have had normal renal ultrasounds." (PMID 34652576, 2021).
colon (1 paper, 2025). "However, their efficacy in colon canceris limited by the chemoresistance associated with βIII-tubulin(TUBB3) upregulation." (PMID 40907950, 2025).
genetic disorders (1 paper, 2023). "This is notable, given the relatively low expression of TUBB3 in cells and that TUBB3 genetic disorders are dominant, altering only 50% of TUBB3 in the neuron." (PMID 37600020, 2023).
TUBB3 also shares sentences with these, for which no sentence is quoted: Lissencephaly (4 papers); schizophrenia (4); head and neck cancer (3); gallbladder cancer (2); kidney cancer (2); lung adenocarcinoma (2); ophthalmoplegia (2); Pachygyria (2); sarcoma (2); schizencephaly (2); squamous cell carcinoma (2); Stroke (2); Vocal cord paralysis (2); anaplastic thyroid carcinomas (1); Anosmia (1); arthrogryposis (1); Ataxia (1); brain cancer (1); brain tumors (1); breast tumour (1); cardiomyopathy (1); cardiovascular diseases (1); cerebellar agenesis (1); Cerebral ischemia (1); cholangiocarcinoma (1); congenital fibrosis of extraocular muscles (1); depression (1); Duane retraction syndrome (1); epileptic seizures (1); female reproductive cancers (1).
A further 36 diseases each share a sentence with TUBB3 in 1 paper.